INS (insulin)
Diseases named in the same sentence as INS in open-access papers (continued):
Sharing a sentence is not in itself a finding about the gene and the disease.
diabetes (continued). "Diabetes mellitus (DM) is a chronic metabolic disorder characterized by an elevated level of blood glucose due to the absence of insulin secretion, ineffectiveness, or lack of uptake of secreted insulin in the body." (PMID 38561662, 2024). "Furthermore, previous clinical trials on Mg2+ supplementation in patients with diabetes and individuals without diabetes showed that Mg2+ supplements can improve blood glucose levels, insulin-related metabolism, and the function of beta cells of pancreatic islets of Langerhans." (PMID 39202546, 2024). "In addition, since RBP4 levels are elevated in the serum of thin, non-diabetic but insulin-resistant individuals with a high genetic risk of developing type 2 diabetes, RBP4 may be useful as an early marker of diabetes risk." (PMID 38966226, 2024). "In a cross-sectional study of Thai subjects with newly diagnosed type 2 diabetes mellitus and impaired glucose tolerance, total body lean mass measured by DXA was inversely associated with glucose levels after oral glucose load independent of insulin secretion and sensitivity." (PMID 39188637, 2024). "As a specific type of DM, gestational diabetes mellitus (GDM) occurs as a result of increased insulin resistance and impaired compensatory increase in insulin secretion during pregnancy, which is a metabolic disorder considered to occur in the pre-diabetic period." (PMID 39157677, 2024). "Diabetes mellitus (DM) is a long-term metabolic condition characterized by hyperglycemia due to an absolute or relative lack of insulin." (PMID 39867069, 2024). "The patient was started on fluid resuscitation and intravenous insulin and was admitted to the intermediate care unit for close monitoring and study of this new-onset diabetic ketoacidosis and subacute encephalopathy in a patient, with no previous history of diabetes." (PMID 39006601, 2024). "Moreover, other diabetes drugs such as metformin or insulin were not included in the analysis." (PMID 38256566, 2024). "However, the influence of ICI on insulin synthesis and secretion in patients with cancer without diabetes remains unknown." (PMID 39722806, 2024). "Diabetes mellitus (DM) is a dangerous chronic disorder in which the body does not create enough insulin or does not use the insulin that it produces adequately." (PMID 38033448, 2023). "Diabetes mellitus (DM) is one of the most prevalent diseases, in which the body either does not produce enough insulin or resists its action." (PMID 37240813, 2023). "The findings of this study suggest higher protein intakes may also help adolescents with T1D improve their post-exercise glycemic response, especially among female adolescents and also among those who do not utilize insulin pumps in their diabetes care, and those with overweight or obesity." (PMID 37111199, 2023). "In addition, emerging evidence has been reviewed to show that the modulatory effect of insulin on GABA/glutamate is important for long-term memory consolidation, whilst deterioration of insulin signaling leads to degenerative disorders, especially in aging patients with diabetes." (PMID 36984824, 2023). "The retrospective study included 186 patients with type 2 diabetes mellitus (DM) with inadequate glycemic control on metformin and basal insulin (degludec, glargine 100, glargine 300) who were switched to fixed-ratio combination GLP-1 RA and basal insulin." (PMID 36726134, 2023). "Diabetes mellitus (DM) is a multifactorial disease in which body fails to release or respond to insulin." (PMID 37139232, 2023). "Diabetes mellitus (DM) is a chronic condition that occurs when the body no longer generates enough insulin or when the insulin produced cannot be used adequately." (PMID 37894680, 2023). "Additionally, BMI-SDS significantly increased by diabetes duration in female participants only (mean ± SD: <2 years 0.39 ± 0.05; 2–5 years 0.49 ± 0.04; and >5 years 0.60 ± 0.04; p<0.0001) and BMI-SDS increased more during insulin therapy (0.44 vs 0.18, p<0.0001)." (PMID 36700969, 2023).
diabetes (continued). "However, our findings in this meta-analysis involving diabetes patients did not reflect the conclusion that glucose-insulin mechanism may improve in people with T2DM after undergoing resistance training." (PMID 37234057, 2023). "However, the higher risk of pancreatic cancer might also be attributable to severe diabetes conditions rather than insulin use." (PMID 37481610, 2023). "However, sex, diastolic blood pressure, heart rate, and history of smoking and drinking were similar among the three groups, irrespective of their diabetes status and whether they were prescribed insulin (all P > 0.05)." (PMID 37542280, 2023). "Diabetes mellitus (DM) is characterized by an absolute or relative lack of insulin creation as well as insulin resistance (IR) in target tissues, which leads to hyperglycemia and glucose intolerance." (PMID 38273819, 2023). "Diabetes mellitus (DM) is a metabolic disorder where the body does not produce adequate levels of insulin or does not effectively respond to the insulin being produced." (PMID 37765290, 2023). "For example, some individuals without a diabetes diagnosis code who filled a single non‐insulin glucose‐lowering medication prescription before a fracture may have been misidentified as persons without diabetes, if the T2D code was not registered within 3 months of the fracture." (PMID 38025040, 2023). "Given its potential insulin sensitizing effects berberine may be useful in intervention for early stages of insulin resistance in patients who have not been diagnosed with diabetes." (PMID 37679692, 2023). "More than 90% of DM cases are classified as type 2 diabetes mellitus (T2DM), characterized by insufficient insulin production by pancreatic β-cells, inadequate insulin secretion, and tissue resistance to insulin." (PMID 37854744, 2023). "However, if a body can no longer produce insulin or becomes resistant to insulin, a serious metabolic disorder from unregulated blood glucose level may occur, which is termed diabetes." (PMID 36437048, 2023). "Similarly, a negative correlation has been shown between ALT and insulin sensitivity using the euglycemic hyperinsulinemic clamp, which may contribute to the development of diabetes." (PMID 37763285, 2023). "Therefore, the presence of autoantibody-negative diabetes that requires insulin after COVID-19, in conjunction with the histological results, implies that, at least in some people, COVID-19 may be linked with islet-cell functional impairment or destruction." (PMID 37916248, 2023). "The underlying pathobiological mechanism for this induced diabetes in COVID-19 patients has not been clearly delineated although it is suspected that SARS-CoV-2 could damage the beta cells of the pancreas and precipitate insulin resistance." (PMID 36947108, 2023). "Therefore, Once-Weekly Insulin Icodec presented with a notable 6.60% increase in TIR compared with Once-Daily Insulin Glargine U100, result that could indicate a potential reduction in diabetes complications." (PMID 37249450, 2023). "Finally, this work could pave the way to test these epitopes in early stage T1D patients (stage 1 or 2) who have islet autoantibodies but no overt clinical diabetes requiring treatment with exogenous insulin." (PMID 36969220, 2023). "Diels, decreased hyperglycemia, stimulated insulin secretion, promoted hepatic glycogen synthesis and attenuated fat accumulation, indicating that ASP could be used as the functional food or in prescriptions for the prevention or treatment of liver diseases and diabetes." (PMID 37202792, 2023). "However, limitations of this calculator include lack of validation for non-European poluations, those diagnosed with diabetes above 35 years, those with other forms of monogenic diabetes, and weaker performance in insulin-treated patients where the probability of type 1 diabetes is high." (PMID 37794142, 2023).
diabetes (continued). "There are two major types of DM, the first being type 1 diabetes (T1DM), characterized by hyperglycemia due to the autoimmune destruction of pancreas beta cells, resulting in the overall decreased production of insulin." (PMID 36902074, 2023). "Consequently, β-cell compensation could not work efficiently for the decreased insulin sensitivity, which resulted in inducing OS and decreasing CAT activity-linked diabetes." (PMID 37432193, 2023). "In addition to injectable preparations such as insulin and insulin analogs, glucagon-like peptide 1and oral hypoglycemic drugs, such as peptidyl peptidase-4 (DPP-4) inhibitors and sodium-glucose co-transporter 2 (SGLT2) inhibitor, are commonly used to treat diabetes." (PMID 37497112, 2023). "A combination study of genomic and transcriptomic analysis presented a positive correlation between the circulating transcript of IGF2BP2 and fasting insulin in individuals without diabetes, suggesting that IGF2BP2 might take part in the pathophysiology of T2DM before the onset of the disease." (PMID 36891946, 2023). "Moreover, risk factors for type 2 diabetes, such as obesity and aging, could also affect the methylome in non-diabetic subjects, which might trigger impaired insulin secretion, insulin resistance, and the progression of diabetes." (PMID 36875456, 2023). "Stroke incidence was 0.58%/year in patients without diabetes, 0.64%/year in diabetic patients not receiving insulin (HR 1.11, 95% CI 0.72–1.71, p = 0.64 vs no diabetes) and 1.80%/years in diabetic patients receiving insulin (HR 3.11, 95% CI 1.91–5.07, p < 0.0001 vs no diabetes)." (PMID 35976428, 2023). "Diabetes mellitus (DM) is a serious health condition in which the body is unable to metabolize carbohydrates either due to lack of insulin production or abnormal insulin signaling." (PMID 37372908, 2023). "The role of Mg2+ in controlling insulin secretion has only been investigated in a limited number of clinical studies; furthermore, the beneficial effect of Mg2+ supplementation on β-cell function in individuals without diabetes was only observed in a small randomized clinical trial." (PMID 37443824, 2023). "Diabetes mellitus (DM) is a noncommunicable disease that occurs when the pancreas is unable to produce enough insulin hormones or when the body is unable to use insulin effectively." (PMID 37940866, 2023). "In this secondary analysis of ClinicalTrials.Gov NCT02192424, adults with ≤5-years diabetes duration were randomized to 3-weeks induction insulin therapy (glargine/lispro) followed by metformin maintenance either with or without intermittent 2-week courses of insulin every 3-months for 2-years." (PMID 37500612, 2023). "Diabetes mellitus (DM) is defined as a disorder characterized by insufficient production of insulin or lack of normal response to it in body, leading blood glucose level to be abnormally high." (PMID 37635255, 2023). "Type 1 diabetes mellitus (T1DM) is an autoimmune disease characterized by an uncontrolled inflammatory response, whereby pancreatic β cells are damaged or destroyed by the immune system causing insulin levels to be severely limited or absent with resultant hyperglycemia." (PMID 37999431, 2023). "Diabetes Mellitus (DM) is a chronic metabolic condition characterised by a lack of insulin, the absence of insulin, or resistance to insulin." (PMID 37048153, 2023). "At this point it is important to state that, the development of well-established type 1 diabetes, where patients are continuously treated with insulin due to the absence of beta cell reservoirs, may differ from the onset of the disease, and more importantly, from other types of diabetes." (PMID 37244952, 2023). "The reason could be that non-adherence to anti-diabetes medication may expose the patient to high blood glucose levels due to increasing glucose production from the liver, decreasing insulin secretion from the beta-cells, or decreasing glucose uptake by skeletal muscles." (PMID 36843610, 2023).
diabetes (continued). "Recent research suggests that a combination of insulin resistance and possible issues with insulin secretion may be responsible for the development of hyperglycaemia in COVID-19 patients who did not previously have diabetes." (PMID 37511334, 2023). "However, since our participants were patients with poorly controlled diabetes, even if the insulin or C-peptide levels were available, they might not have reflected the true levels of insulin resistance due to the so-called glucose toxicity." (PMID 37993771, 2023). "As mentioned in the current review, isocaloric TRE, particularly in individuals with prediabetes, improves fasting insulin and insulin resistance independent of weight loss, but with a controversy on the glucose profile in participants scheduled for ad libitum TRE who do not have diabetes." (PMID 37488260, 2023). "This raises the question of whether the measurement of blood insulin levels should not be included in mandatory medical certification tests along with glucose levels in order to be able to prevent the development of diabetes earlier, albeit in a group of obese soldiers." (PMID 37887427, 2023). "Diabetes mellitus (DM) is a chronic condition in which the body fails to produce and respond to insulin, resulting in elevated glucose levels." (PMID 37761009, 2023). "However, a body with diabetes does not produce enough insulin or cannot effectively use insulin." (PMID 37608402, 2023). "While insulin secretion was enhanced in typical cases of Cushing's syndrome and steroid-induced diabetes, it is plausible to speculate that GR-regulated NECAB1 expression in β-cells may have a pathophysiological role in diabetes development in some stages of the disease." (PMID 37863964, 2023). "Diabetes mellitus (DM) is a group of metabolic diseases characterized by hyperglycemia due to a total or relative lack of insulin secretion and insulin resistance or both according to the World Health Organization (WHO)." (PMID 37790148, 2023). "Overall, these results suggest that patients with diabetes could have inadequacies in upregulating cerebral glycolysis and glucose metabolism due to an absence of insulin signaling or reduced GLUT levels, and such a dysfunction may be related to neurodegeneration and the development of dementia." (PMID 37869511, 2023). "Metformin, a plant-derived compound, is widely used to decrease blood sugar levels and indirectly reduce diabetes mellitus (DM), a global health problem provoked by hyperglycemia and characterized by the absence of or resistance to insulin." (PMID 36676085, 2023). "Patients who do not carry a diagnosis of diabetes and who require a low-dose insulin infusion to maintain their glycemic target might not need a basal insulin dose but might require correctional subcutaneous insulin when transitioning to the regular nursing floor." (PMID 37120562, 2023). "HOMA2-IR was higher and Gutt-ISI was lower in subjects of the overweight/obese-high VF group which confirmed that in subjects with higher VF, even though insulin secretion is higher, their β-cells could not compensate fully for decreased insulin sensitivity, thus leading to diabetes." (PMID 36909323, 2023). "Importantly, in the in vivo study using diabetes rat models induced by streptozotocin (STZ), the nanoparticles could reduce the glucose blood level to the normal rate, increase the resistance of insulin and the resistance of plasma fibroblast growth factor 21 (FGF 21), compared to the free form." (PMID 37346355, 2023). "Diabetes Mellitus (DM) is a chronic disease that occurs either when the pancreas does not produce enough insulin or when the body cannot effectively use the insulin it produces." (PMID 38146457, 2023).
diabetes (continued). "Moreover, during COVID-19 infection a decrease in insulin secretion is also observed, due to the secretion of counteracting hormones and the activation of the Renin-Angiotensin-Aldosterone (RAAS) system, effectively destroying pancreatic β-cells, which leads to newly diagnosed diabetes." (PMID 37587391, 2023). "Therefore, liraglutide treatment appears to have beneficial effects on pancreatic islet morphology and insulin content that are consistent with protection against the development of overt diabetes, while GH treatment did not produce any added beneficial effects on these parameters." (PMID 36480511, 2023). "Therefore, we are confident that we are not overestimating diabetes requiring insulin therapy, though we may miss some in younger age groups if these children got their prescriptions in hospital." (PMID 36869270, 2023). "On the other hand, recent findings from studies on novel subtypes of adult diabetes suggested that insulin-resistance mechanisms rather than glucose-dependent pathways may significantly impact predisposition to kidney dysfunction, thus more data may be beneficial to support this association." (PMID 37452207, 2023). "Diabetes mellitus (DM) is a metabolic disease characterized by prolonged hyperglycemia due to either inadequate production of insulin by the pancreas or the cells of the body not responding properly to the produced insulin." (PMID 35687581, 2022). "Similarly, we omitted diabetes-specific emotional problems, such as diabetes burnout, fear of hypoglycaemia, negative perceptions of insulin therapy, satisfaction with treatment and diabetes distress, which should also be considered in precision medicine in diabetes." (PMID 35729420, 2022). "Among the various types of diabetes, all characterized by high blood glucose levels, the main two types are type 1 diabetes, an autoimmune condition where the pancreas produces little or no insulin, and type 2 diabetes, a metabolic disorder that results in hyperglycaemia due to insulin resistance." (PMID 36226124, 2022). "There are mainly two types of diabetes: type 1 is juvenile diabetes, an autoimmune disorder, often referred to as insulin-dependent diabetes mellitus; and type 2 is adult-onset diabetes, which results from defective insulin secretion, and can be insulin or non-insulin dependent." (PMID 35056780, 2022). "Additionally, it has been shown that such a reduction in insulin biosynthesis and secretion together with a reduction in PDX-1 and MafA is preserved by mitigating pancreatic β-cell failure with insulin preparation or SGLT2 inhibitors, especially in the early stage of diabetes mellitus." (PMID 35453568, 2022). "We hypothesized that GLUT4 and/or levels of proteins involved in sorting GLUT4 into the GSC may be impaired in skeletal muscle of patients with diabetes and have tested this in obese people with and without T2D characterized using an insulin suppression test (IST)." (PMID 35964329, 2022). "In particular, ART could influence the methylation and, therefore, the expression of imprinted and non-imprinted genes that may be involved in insulin signaling pathways and adipocyte differentiation, suggesting a role of these procedures in the development of diabetes and future obesity." (PMID 36078985, 2022). "However, insulin should not be withheld from patients who cannot meet their glucose goals using other agents, and insulin should be used in any patient exhibiting the symptoms of uncontrolled diabetes (i.e., polyuria, polydipsia, or polyphagia)." (PMID 34922811, 2022). "Reduction of insulin level and dysregulated insulin signaling activity both in diabetic or non-diabetic older individuals diminishes the anabolic capacity of insulin to alleviate MPB in skeletal muscles and may possibly be a primary mechanism shared by age-related sarcopenia and diabetes." (PMID 36482911, 2022).